MMP9 (matrix metallopeptidase 9)
Diseases named in the same sentence as MMP9 in open-access papers (continued):
Sharing a sentence is not in itself a finding about the gene and the disease.
aortic aneurysm (65 papers, 2009 to 2026). A ruptured aneurysm located in the wall of the proximal portion of the descending aorta proceeding from the arch of the aorta. "The underlying mechanism possibly involves JAK2 V617-positive circulating leukocytes that demonstrate upregulation of genes associated with aortic aneurysm formation, including matrix metalloproteinase 9 (MMP-9)." (PMID 40135024, 2025). "MMP9, a marker of vascular inflammation elevated in AD conditions, is linked to other vascular disease conditions like aortic aneurysm, vascular stenosis, and vascular calcification." (PMID 39766777, 2024). "Chronic inflammation and MMP2 and MMP9 activation are the hallmark pathological process of aortic aneurysms." (PMID 39011492, 2024). "MMP9 appears associated with the development of aortic aneurysms, because its suppression prevents the development of aortic aneurysms." (PMID 38540232, 2024). "Overexpression of MMP2 in smooth muscle cells and MMP9 in neutrophils and macrophages can cause degenerative changes in the middle layer of the artery in aortic aneurysms, and knockout of MMP2 and MMP9 can inhibit the development of thoracic aortic aneurysms." (PMID 35463768, 2022). "In another study, although the cleavage site of pro-MMP-9 was unclear, the elastase-induced aortic aneurysm was significantly attenuated in mouse chymase-deficient mice." (PMID 36289761, 2022). "A 2018 case-control study reported a close association between serum MMP9 and the existence of aortic aneurysms, suggesting a role for this isoform as a valuable marker for the discrimination of aortic aneurysm, especially for TAA." (PMID 35892496, 2022). "In a previous study, progression of aortic aneurysms induced by elastase was significantly attenuated in MMP-9-deficient mice." (PMID 36289761, 2022). "Increased viability of MMP-2 can cause arteries to dilate, and increased vitality of MMP-9 can cause rupture of aortic aneurysms." (PMID 33403385, 2021). "The objective of this study was to evaluate the interactions between TLR4 and MMP9 polymorphisms in the risk of aortic aneurysm (AA) and its subtypes." (PMID 30922233, 2019). "In this study, we investigated the serum levels of MMP9 in aortic aneurysm to evaluate its predictive and diagnostic efficacy for AAA and TAA, and explored the association of MMP9 with circulating laboratory markers." (PMID 30373522, 2018). "Multiple logistic analyses further suggested that serum MMP9 was an independent risk factor for aortic aneurysm." (PMID 30373522, 2018). "To further assess the clinical application value of serum MMP9 in aortic aneurysm, we explored its predictive and diagnostic efficacy for identifying AAA or TAA." (PMID 30373522, 2018). "That approach was already demonstrated to be clinically effective in vascular diseases associated with MMP-9 hyperactivity—aortic aneurysm and chronic wounds healing." (PMID 25650123, 2015). "Previous studies reported activation of MMP-2 and MMP-9 being associated with formation of aortic aneurysms." (PMID 26539497, 2015). "Possibly related to the abundance of NGAL/MMP-9 complexes associated with human aortic aneurysms, which may find their way into the bloodstream, Chang and colleagues have reported increased bNGAL values in all patients after stent graft insertion." (PMID 25960881, 2014). "Significant increases in chymase and MMP-9 activities were also observed in a mouse aortic aneurysm model that was developed by continuous administration of angiotensin II to apolipoprotein E-deficient mice, and expansion of the aortic aneurysm was also prevented by chymase inhibitors." (PMID 36289761, 2022). "Therefore, serum MMP9 may be a valuable diagnostic biomarker for aortic aneurysm, especially for TAA." (PMID 30373522, 2018). "Therefore, MMP9 might be a useful biomarker with clinical predictive and diagnostic value for aortic aneurysm, especially for TAA." (PMID 30373522, 2018).
aortic aneurysm (continued). "MMP-2 and MMP-9 contribute to the pathogenesis of aortic aneurysm by cleaving the extracellular matrix of blood vessels." (PMID 37294581, 2023). "In a mouse model of aortic aneurysm/dissection, the lesioned aortic tissue was accompanied by elastic lamina degradation, increased macrophage infiltration, and elevated expression of MMP9 and MMP2." (PMID 36830768, 2023). "In the normal aorta, elastic fibers maintain the vascular wall structure, while augmentation of MMP-9 expression leads to the elastic fiber disruption seen in human aortic aneurysms." (PMID 36289761, 2022). "In a dog elastase-induced aortic aneurysm model, both MMP-9 and chymase activities were significantly increased, and chymase inhibition significantly attenuated expansion of the aortic aneurysm, along with a reduction in chymase and MMP-9 activity." (PMID 36289761, 2022). "In the same study, in the study subgroup of patients with an aortic aneurysm/dissection (seven patients with a bicuspid aortic valve and six patients with a tricuspid aortic valve), only a significant augmentation of MMP-9 expression was noted." (PMID 35563383, 2022). "MMP-9 activity was also time-dependently increased in an extract of human aortic aneurysms, suggesting the existence of MMP-9-activating enzymes in extracts from human aortic aneurysms." (PMID 36289761, 2022). "On the other hand, TGF-β signaling pathway activation stimulates MMP-2 and MMP-9 production, which both determine matrix degradation, a key milestone in aortic aneurysm formation." (PMID 35563383, 2022). "We next examined intra-aortic gene expression of MMPs and TIMPs, which are presumed to be involved in aortic aneurysm formation and observed that Ccl3−/− mice exhibited significantly enhanced intra-aortic Mmp9 mRNA expression compared with WT mice." (PMID 33239616, 2020). "Based on ROC curves, elevated MMP9 levels suggested a higher specificity than sensitivity in recognizing either AAA or TAA, which represented that serum MMP9 conferred a crucial role in safely ruling out aortic aneurysm." (PMID 30373522, 2018). "Matrix metalloproteinase-9 (MMP9) has been reported to play a key role in the pathogenesis of aortic aneurysm." (PMID 30373522, 2018). "Further prospective studies based on larger scale cohorts will be needed to validate the clinical applicability of serum MMP9 on the identification of aortic aneurysm initiation and progression in the future practice." (PMID 30373522, 2018). "Meanwhile, we intended to determine the relationship between serum MMP9 and other laboratory markers to discuss their possible interaction relevant for aortic aneurysm." (PMID 30373522, 2018). "Along these lines, targeted disruption of the MMP9 gene in bone marrow derived cells protects mice fed a high fat diet and infused with angiotensin II from development of aortic aneurysms." (PMID 29073282, 2017). "MMPs are typical proteases which potently degrade a variety of ECM proteins, and previous studies suggested that MMP-9 played a central role in the formation of aortic aneurysm." (PMID 27336852, 2016). "MMP-9 regulates vascular remodeling including ischemia-induced angiogenesis, aortic aneurysm development and atherosclerotic plaque rupture." (PMID 26406902, 2015). "Nevertheless, involvement of mediators of vascular remodeling, for example, metalloproteinases 2 and 9 (MMP-2 and MMP-9), as well as oxidative stress has also been shown in studies investigating aortic aneurysm specimen." (PMID 26539497, 2015). "A recent study showed attenuation of experimental aortic aneurysm formation in mice after use of unsaturated fatty acid causing reduced expression of MMP-2 and MMP-9." (PMID 26539497, 2015). "Increased activity of Mmp9 compromises vascular integrity in cardiovascular pathologies including aortic aneurysm, and can promote rupture of atherosclerotic plaques." (PMID 25359725, 2014).
aortic aneurysm (continued). "Both MMP-2 and MMP-9 are also overexpressed in different Ang II infusion induced aortic aneurysm and aortic dissection models." (PMID 24194850, 2013). "In particular, several lines of evidence have shown that MMP9 (collagenase type IV or gelatinase B) is activated in human aortic aneurysms." (PMID 23442769, 2013). "Previous reports have demonstrated that MMP-2 and MMP-9, which are respectively derived from SMCs and macrophages, play important roles in the progression of aortic aneurysms." (PMID 22570740, 2012). "Thus, Tet2-driven clonal hematopoiesis accelerated aortic aneurysm progression through MMP9-producing, osteoclast-like macrophages and therefore represents a tractable therapeutic axis." (PMID 41739588, 2026). "Third, in mice, IH was demonstrated to increase vascular cell production of matrix metalloproteinases (MMPs) and metalloproteinases, including ADAM‐17 and the elastases MMP2 and MMP9, resulting in alteration of elastin in the aortic wall and the development of aortic aneurysms." (PMID 41541542, 2026). "Additionally, riboflavin inhibits the activity of matrix metalloproteinase-9 (MMP-9), an enzyme that degrades the extracellular matrix and promotes the development of aortic aneurysms." (PMID 40871724, 2025). "Moreover, experimental studies conducted on mice showed that both MMP-2 and MMP-9 act complementarily in aortic aneurysm development." (PMID 35563383, 2022). "Recent studies have shown that the depletion of KIAA1462 decreased the expression of genes such as VCAM1, which is involved in the pathogenesis of ascending aortic aneurysm through increasing the activity of MMP-2 and MMP-9 that promotes aortic aneurysm progression." (PMID 35741789, 2022). "This cytokine increases MMP-9 activity during aortic aneurysms and ruptures in mice." (PMID 33708378, 2021). "Therefore, MMPs, especially MMP1 and MMP9, have been widely considered critical factors in the initiation and development of aortic aneurysms." (PMID 33029260, 2020). "Besides, gelatin zymography was used to measure activity of MMP-2 and MMP-9 in the wall of aortic aneurysms." (PMID 32382533, 2020). "In addition, genetic deletion of the MCP-1 receptor C–C motif chemokine receptor 2 (CCR2), IL-6, or MMP-9 ameliorated aortic aneurysm pathogenesis." (PMID 29296021, 2018). "Serum MMP9 was closely related to the existence of aortic aneurysms and could be a valuable marker for the discrimination of aortic aneurysm, especially for TAA." (PMID 30373522, 2018). "To date, circulating biomarkers, such as C-reactive protein (CRP), homocysteine (Hcy) and Cystatin C (Cys-c), have been analyzed in aortic aneurysmal diseases, but it remains unclear whether the studied biomarkers are correlated with serum MMP9." (PMID 30373522, 2018). "MMP-2 and MMP-9 work in concert to produce aortic aneurysms." (PMID 29190959, 2017). "Indeed, our results also showed UCP-2 knockout up-regulated the MMP2 and MMP9 expression in aortic aneurysm." (PMID 28683125, 2017). "UCP-2 knockout up-regulated the MMP2 and MMP9 expression in aortic aneurysm." (PMID 28683125, 2017). "As plasma MMP8 and MMP9 were similar in patients with uncomplicated aortic aneurysm and in patients with other unspecific diagnoses having a regular aortic size, aortic dilation per se does not appear as a major determinant of plasma MMP8 and MMP9 in the selected population of patients." (PMID 23442769, 2013). "Therefore, MMP-9 is thought to play a critical role in the progression of aortic aneurysms." (PMID 36289761, 2022). "The main MMPs involved in aortic aneurysms are gelatinase A (MMP-2) and gelatinase B (MMP-9) and both are capable of degrading the extracellular matrix because they elevate elastolytic and collagenolytic activity when compared with normal aortic tissue." (PMID 40521351, 2025).
aortic aneurysm (continued). "Western blotting results revealed that NLRP3, MMP2 and MMP9, which induced the degradation of extracellular matrix (ECM), were dramatically increased in the human and mouse aortic aneurysm tissues compared with non‐aneurysmal tissues." (PMID 39601144, 2024). "In agreement with this, several studies reported an increased expression and activity of MMP-1, MMP-2, MMP-3, MMP-9, and MMP-12 in aortic aneurysm tissues." (PMID 35456498, 2022). "The decreased macrophage infiltration in resolving thrombi from MMP-9-/- animals is consistent with the key role of MMP-9 in macrophage migration in vivo in models of peritonitis, spinal cord injury and aortic aneurysms." (PMID 26406902, 2015). "Both MMP-9 and PTX3 could be of relevance for the pathogenesis of aortic aneurysms, potentially through interacting mechanisms." (PMID 36606286, 2022). "Third, there were no complete records of potential confounders relevant to aortic aneurysm and MMP9 levels, such as the history of smoking and drinking." (PMID 30373522, 2018). "Above evidence might explain our findings that serum MMP9 levels were positively correlated with circulating CRP and Hcy, which could partly reflect the fact that multiple biomarkers responded to aortic aneurysm related events." (PMID 30373522, 2018). "Of note, plasma MMP9 was not increased in patients with uncomplicated aortic aneurysm, suggesting that aortic dilation per se is not sufficient to significantly increase circulating levels of MMP9 in this patient population." (PMID 23442769, 2013). "Furthermore, the TGF-β pathway up-regulates and decreases the MMP-9 expression involved in changes in the ECM, and this may contribute to the protective effect of DM against aortic aneurysm formation." (PMID 34683112, 2021).
oral squamous cell carcinoma (65 papers, 2012 to 2026). "Some research indicates that Gal-7 regulates genes associated with metastasis, like MMP9, thereby enhancing the invasive potential of lymphoma and oral squamous cell carcinoma (OSCC) cells." (PMID 40134029, 2025). "Adjusted association of MMP-9 and 8-OHdG with oral squamous cell carcinoma (OSCC) using multivariable logistic regression models." (PMID 33735248, 2021). "Recent study highlighted that MICAL1 deficiency in oral squamous cell carcinoma arrested MMP9 secretion, vimentin, and E-cadherin levels, consistent with increased N-cadherin." (PMID 31019460, 2019). "A non-significant difference andstatistically comparable values were seen for serum MMP-9 levels in well-differentiated, moderately differentiated and poorlydifferentiated oral squamous cell carcinoma with p=0.07." (PMID 40978635, 2025). "We show that mean salivary MMP-9 levels are seen in subjects with oral squamous cell carcinoma with further higher levels in subjectswith poorly differentiated oral squamous cell carcinoma." (PMID 40978635, 2025). "In the case of butein, a dose-dependent reduction in COX-2 and Matrix metalloproteinase-9 (MMP-9) expression in oral squamous cell carcinoma lines (SAS and KB) was observed." (PMID 38539427, 2024). "These values are in accordance with the clinically relevant MMP-9 concentrations found in patients with oral squamous cell carcinoma (OSCC), under the conditions detailed in the “Methods” section." (PMID 37303001, 2023). "Previous studies have shown that PD reduces the expression of MMP2 and MMP9 to inhibit the invasion and metastasis of human oral squamous cell carcinoma." (PMID 36526799, 2023). "This matrix was selected since the presence of MMP-9 in saliva is clearly indicative of possible diseases such as cancerous pathologies like oral squamous cell carcinoma (OSCC), being proposed as an effective biomarker of such disease." (PMID 37303001, 2023). "Overexpression of common genes associated with tobacco-induced oral squamous cell carcinoma (OSCC), such as MMP1, MMP3, MMP9, YAP1, CYP1A1, and CYP1B1, was also observed." (PMID 36835505, 2023). "Esophageal Cancer: curcumin modulated Notch-1 signaling and suppressed NF-jB and its downstream targets involving Bcl2, cyclin D1, VEGF, and MMP-9 in oral squamous cell carcinomas." (PMID 36712505, 2022). "Comparison of MMP-9 and 8-OHdG values between oral squamous cell carcinoma (OSCC) cases and controls in pre-surgery." (PMID 33735248, 2021). "Reduced Rab1 levels and a commensurate decrease in MMP9 secretion by cultured human oral squamous cell carcinoma cells has been reported." (PMID 29876004, 2018). "A high expression of N-cadherin strongly increases the transcriptional activity of β-catenin and upregulates MMP-9 expression in oral squamous cell carcinoma cells." (PMID 30235848, 2018). "P. gingivalis-mediated immune evasion, apoptosis inhibition, carcinogen conversion, induction of MMP-9 and dysbiosis of the oral microbiota have all been posited as pro-tumorigenic mechanisms in the context of oral squamous cell carcinoma." (PMID 26788120, 2016). "It suggested pretreatment serum levels of MMP-9 as a powerful prognostic marker in patients with oral squamous cell carcinoma." (PMID 27034760, 2016). "TGF-β was shown to induce the expression of MMP9 mRNA but decrease the expression of MMP2 mRNA by human oral squamous cell carcinoma cell lines." (PMID 25493076, 2014). "Thus, individuals with oral squamous cell carcinoma have average salivary MMP-9 levels, andthose with poorly differentiated oral squamous cell carcinoma have even higher levels." (PMID 40978635, 2025). "This study explores the relationship between the alteration of primary cilia and tumourigenesis by investigating primary cilia expression and the role of IFT20 in regulating matrix metalloproteinase 9 (MMP-9) expression in oral squamous cell carcinoma (OSCC) cell lines." (PMID 40017656, 2025).